ENO1 (enolase 1)
Diseases named in the same sentence as ENO1 in open-access papers (continued):
Sharing a sentence is not in itself a finding about the gene and the disease.
infection (continued). "The lack of effect in Δbpe123 replication rate in ENO-1 depleted cells could be explained by the fact that infection with this strain activates ENO-1 but to a lower extent, and probably alternative mechanisms are supporting Brucella replication." (PMID 27900285, 2016). "Furthermore, ENO-1 depletion by siRNA impaired B. abortus intracellular replication in HeLa cells, confirming a role for α-enolase during the infection process." (PMID 27900285, 2016). "Thus, ENO1 can be considered as a response to H. pylori infection and CagA transfection, showing that H. pylori positive gastric mucosal is under stimulation after infection." (PMID 40051725, 2025). "Notably, EV-A71 infection up-regulated ENO1 mRNA expression which could be reduced upon 07-IgG1 treatment." (PMID 35130884, 2022). "In addition, other proteins identified in fungal vesicles might be immunogenic during infection, including C. parapsilosis Adh1 and C. tropicalis Eno1 and Tdh3, thus being potential candidates for future immunodiagnostic tests or vaccines." (PMID 32708393, 2020). "The ENO1 expression level in the gastric cells varied from the MOI and infection duration, which might be attributed to the effect of H. pylori virulence factors on the gastric cells, e.g., changing the balance of cellular proliferation and apoptosis." (PMID 36295613, 2022). "As such, the ENO1 and BAG1 genes, which are well known to be expressed distinctively in the bradyzoite stage during the chronic phase of infection, were highly enriched in the repressive mark H3K9me3 but they were also unexpectedly enriched in the gene activation hallmark H3K14ac." (PMID 29101771, 2017). "We found both mRNA and protein levels of ENO1 were upregulated in EV-A71 but not CA16 infection." (PMID 35130884, 2022). "Among them, we found that several candidates like PR-5, ENO1, TPL3, PIP1, and CHLH/ABAR could be key targets of P. infestans to suppress the host defense/immunity via the transcriptional or translational/post-translational regulation during different infection stage." (PMID 33920680, 2021). "Interestingly, unlike ldh1/ldh2 and eno1/eno2 which are expressed in a stage-dependent manner, both PGM isoforms (pgm1 and pgm2) were upregulated 6.4 and 3.1 folds, respectively, in the chronic stage, 28 days post-infection (dpi)." (PMID 35597992, 2022).
adenocarcinoma (4 papers, 2015 to 2022). A common cancer characterized by the presence of malignant glandular cells. "Hub genes were identified, including GADPH, ENO1, EEF2, and ATP5A1, which showed differential expression in patients with adenocarcinoma of the colon and rectum." (PMID 35445138, 2022).
retinopathy (4 papers, 2012 to 2024). "CAR-linked ENO1 autoantibodies promote retinopathy by inducing retinal cell apoptosis, leading to retinal dysfunction or degeneration." (PMID 33584813, 2020). "These autoantibodies are common in patients with cancer associated retinopathy, where they exert pathogenic effects, and may be triggered by immunodominant peptides within the ENO1 sequence or by posttranslational modifications." (PMID 33584813, 2020).
psychiatric disorder (3 papers, 2013 to 2024). A disorder characterized by behavioral and/or psychological abnormalities, often accompanied by physical symptoms. "Among the proteins identified, both ALDOC and ENO1 have been previously associated with psychiatric disorders." (PMID 34576123, 2021). "The differentially expressed proteins included those previously implicated in psychiatric disorders, such as ALDOC, ENO1, and PRDX2." (PMID 23408933, 2013).
bacterial infection (2 papers, 2019 to 2023). "Taken together our results indicate that upon bacterial infection, eRNA serves as a “bridging molecule” between bacterial ENO and eukaryotic ENO-1 and thereby facilitates pathogen dissemination." (PMID 31106201, 2019).
head and neck tumor (2 papers, 2020 to 2023). "The overexpression of NMRAL2P led to an increase in lactic acid synthesis, and the downregulation of ENO1 led to a decrease in lactic acid production, indicating that NMRAL2P acts on ENO1 to promote head and neck tumor cells." (PMID 37810778, 2023).
infectious disease (2 papers, 2017 to 2025). A disorder directly resulting from the presence and activity of a microbial, viral, or parasitic agent in humans. "Modulation of ENO1 thus provides a potentially effective strategy to boost DC function and promote immunity against infectious and non-infectious diseases." (PMID 28525970, 2017).
neurological disorders (2 papers, 2023 to 2025). "We observed that the observed changes in ALDOA and ENO1 expression could induce various neurological disorders by modulating their direct interactors." (PMID 37664457, 2023).
digestive system cancer (1 paper, 2025). A primary or metastatic malignant neoplasm involving any part of the digestive system. "The present study highlights the potential of ENO1 and CP as effective biomarkers for digestive system cancers." (PMID 40821642, 2025).
neurodegenerative disease (1 paper, 2023). A disorder of the central nervous system characterized by gradual and progressive loss of neural tissue and neurologic function. "The results showed that the single-cell samples of the CA1 subregion were mainly involved in vesicle-mediated transport in synapse and neurodegenerative disease-related functions, and Syn2, Sh3gl2, Aldoa, Tubb2a and Eno1 were screened as the key target genes." (PMID 36768134, 2023).
ENO1 also shares sentences with these, for which no sentence is quoted: Behcet disease (6 papers); squamous cell carcinoma (4); atherosclerosis (3); colorectal (3); Crohn disease (3); cyst (3); Hashimoto's encephalopathy (3); inflammatory bowel disease (3); metabolic disorders (3); neuroendocrine tumors (3); B cell lymphoma (2); benign tumors (2); cardiovascular disease (2); depression (2); heart attack (2); metastasis (2); nasopharyngeal carcinoma (2); osteoporosis (2); systemic lupus erythematosus (2); ulcerative colitis (2); Wilms tumor (2); acral lentiginous melanoma (1); allergies (1); amyotrophic lateral sclerosis (1); arrhythmogenic right ventricular cardiomyopathy (1); autoimmune cardiomyopathies (1); autoimmune hepatitis (1); autoimmune pancreatitis (1); Barrett adenocarcinoma (1); carcinoma in situ (1).
A further 61 diseases each share a sentence with ENO1 in 1 paper.